PAX8 (paired box 8)
Diseases named in the same sentence as PAX8 in open-access papers (continued):
Sharing a sentence is not in itself a finding about the gene and the disease.
tumor (continued). "The expression distribution of malignant markers of OC (WFDC2 and PAX8) and pathological identification enabled us to determine the aggregated areas of tumor cells." (PMID 39773329, 2025). "These assays revealed the tumor cells in the cerebellar lesion showed expression of PAX8 along with focal expression of CA9 (23.7%) and CD10 (4.4%)." (PMID 39833894, 2025). "The immunohistochemical results showed that the tumor was positive for PAX8, CA9 (diffuse box-like positivity), CK7, CD10, P504S, and vimentin." (PMID 41306531, 2025). "In our case, the tumor displayed extensive tubular growth, low-grade cytology, and PAX8/CK7 negativity-features that strongly resemble FATPWO." (PMID 40959354, 2025). "The predominant tumor cell type in the brain metastasis, accounting for 65.4% of the tumor cells, was PAX8+CA9−CD10−PanCK−CD56−Ki-67+, and these cells were completely absent in the liver metastasis." (PMID 39833894, 2025). "Tumor cells also showed diffuse positivity for vimentin and PAX8 and focal positivity for CK7 and CD10." (PMID 40361930, 2025). "Immunohistochemical staining showed tumor cells were positive for PAX8, CA9, CK7, and AMACR (also referred to as P504S), partially positive for CD10, and negative for TFE3 and CD117." (PMID 41357565, 2025). "Detectable PAX8 expression is considered a strong argument for a tumor origin from the kidney, thyroid, or inner female genital tract." (PMID 39105782, 2024). "This heterogeneity was reflected in the variable expression of markers such as PCK, EMA, CK7, 34βE12, and Pax-8 across different regions of the tumor, indicating diverse cellular phenotypes and potential differences in tumor cell biology." (PMID 39850820, 2024). "Firstly, we performed H&E and immunohistochemical staining on the cancer tissue, exhibiting stronger staining of PAX8, indicating that the tumor is serous cancer." (PMID 38082211, 2024). "The tumor cells were positive for PAX8, weakly and focally positive for CK20, CKAE1/AE3, CD10, and AMACR, and negative for CK7, CD117, MelanA, HMB45, TFE3, Actin, and ALK." (PMID 38892169, 2024). "For many tumor types, however, the reported frequencies of PAX8 positivity vary considerably, which makes it practically impossible to derive the prevalence of PAX8 expression in a particular tumor type from the literature." (PMID 39105782, 2024). "In summary, the standardized assessment of PAX8 staining in 149 different tumor types and subtypes enabled us to define a ranking order with respect to the frequency of PAX8 immunostaining in tumors." (PMID 39105782, 2024). "PAX8 staining of the lung tissues confirmed the PTC cells origin of metastasized tumours, which was hardly detectable after miR‐31 KO." (PMID 38797942, 2024). "Specifically, PAX8 expression, a marker of tumor cells (serous, endometrioid, and clear cell OvCa) derived from the fallopian tube secretory cell and less frequently expressed in benign pathologies, was detected in all OvCa cases, but solely in 1 control." (PMID 38564289, 2024). "The large scale of our study enabled a ranking list of human tumor entities according to the prevalence of positive PAX8 immunostaining." (PMID 39105782, 2024). "Overall, the METTL3/PAX8/YTHDC1 axis has been revealed to play a pivotal role in repressing tumour occurrence, and is antagonized by miR-493-5p." (PMID 38993572, 2024).
tumor (continued). "Sporadic reports on a possible prognostic impact of PAX8 in different tumor types and the availability of a clinical database to our TMAs prompted us to search for possible associations between PAX8 expression and cancer aggressiveness." (PMID 39105782, 2024). "Overall, 40 (26.8%) of 149 tumor categories showed detectable PAX8 expression with 32 (21.5%) tumor categories including at least one case with strong positivity." (PMID 39105782, 2024). "The expression of PAX8 tumor marker showed a clear separation between the tumor cells and other cell populations also in this “integrated patient” case." (PMID 39362905, 2024). "For example, down-regulation of PAX8 gene expression has been reported to reduce the ability of tumor cells to migrate and adhere to the ECM, thereby reducing anoikis resistance." (PMID 37179119, 2023). "Dermatohistopathological examination of skin biopsies revealed a diffuse and nodular infiltrate of pleomorphic atypical tumour cells with strong expression of cytokeratin 7 and PAX8, also detectable within lymphatic vessels." (PMID 37013123, 2023). "PAX8 deficiency can also decrease the amount of TGF-beta secretion, which is a cytokine that is crucial for the modification of the tumor microenvironment." (PMID 37891636, 2023). "In contrast, both CHEK1 and PAX8 appear to associate positively with PDAC aggressiveness and poor prognosis, based on the deleterious effects of their elevated expression in tumor grade progression and overall survival." (PMID 36831395, 2023). "Our patient’s staining pattern was PAX-8( +)/TG( −)/TTF-1( −)-supported RCC as the origin of the tumor." (PMID 37990226, 2023). "In conclusion, our study demonstrates that SMARCB1 is a key regulator of the renal enhancer program, which defines the context in which PAX8 is required for tumor growth." (PMID 37554444, 2023). "Analysis of the online data revealed that PAX2 and PAX8 were expressed at relatively high levels in RCC tumor tissues compared to other PAX genes, while PAX6 was expressed at lower but still significant levels." (PMID 37511191, 2023). "In such instances, macrophage markers, such as CD68 or CD163, and markers for follicular cell lineage, TTF-1, PAX8, and thyroglobulin, can help to confirm the presence of tumor cells within a vessel lumen." (PMID 37324272, 2023). "Tumor growth in vivo was totally abrogated by PAX8 KD (P81Ctrl(A)), partially rescued for P81Ctrl(LT) cells and completely rescued for P81S11(LT) cells, which were transduced with the more efficient SMARCB1 sgRNA." (PMID 37554444, 2023). "Chromatin immunoprecipitation with sequencing (ChIP-seq) analysis of xenografted ccRCC tumours revealed that PAX8 and HIF2A colocalized on chromatin substantially more frequently than what would be expected by chance." (PMID 35676472, 2022). "Superovulation, while also achieving a 100% tumorigenesis rate, resulted in a similar severity of local tumorigenesis as measured by the area of PAX8+ tumor lesions." (PMID 35682896, 2022).
tumor (continued). "FOXJ1 and CAPS expression levels also decreased with increasing tumor grade while PAX8 levels increased with tumor grade." (PMID 36552773, 2022). "RT-PCR revealed that the expression of hsa-miR-326 was reduced, and PAX8 was significantly increased in BC tumor tissues compared with normal tissues." (PMID 35154515, 2022). "Pathological characteristics of organoids including H&E staining and expression of protein markers (CK20, CDX-2, STAB2, CD7, PAX8) were consistent to those of the original tumor." (PMID 35721089, 2022). "Experimental results showed that the expression level of PAX8 in tumor tissues was significantly decreased after Curcumol treatment." (PMID 35548853, 2022). "The tumour cells were diffusely and strongly positive for PAX8 (MRQ-50, Cell Marque, RTU), Pan cytokeratin (AE1/AE3, Thermofisher, RTU)." (PMID 34514562, 2022). "For the metastatic MLA in the lung in case 3, the tumor cells were positive for PAX8, GATA3, and TTF1, in accordance with the immunoprofile of the primary tumor of the uterine corpus." (PMID 35865471, 2022). "We also evaluated PAX2 and PAX8 immunostainings related to age, gender, tumor size, and histomorphologic tumor characteristics." (PMID 34306127, 2021). "The only statistically significant relationship we found was between PAX8 expression and tumor size, and the frequency of expression of this marker increased significantly as the tumor size increased." (PMID 34306127, 2021). "The only statistically significant relationship was found between PAX8 expression and tumor size (P=0.033)." (PMID 34306127, 2021). "Positive PAX8 results were correlated with high tumor grade (P = 0.002), type 2 tumor subtype (P < 0.0001), and lymphovascular invasion (P = 0.0186)." (PMID 34540435, 2021). "Histology of HGSC tumor revealed positivity for Pan-CK, markers of Mullerian epithelium (PAX8, WT1) and Ki67, as well as the markers of aggressiveness, matrix metallopeptidase (MMP) 9 and MMP2." (PMID 33530497, 2021). "The PAX8 gene was found to be overexpressed in different tumor types, including thyroid and renal carcinomas, ovarian epithelial carcinomas, and pancreatic neuroendocrine tumors." (PMID 34540435, 2021). "Using NIH-OVCAR3 cells bearing doxycycline-inducible shRNAs against PAX8 or MECOM confirmed that PAX8 silencing leads to profound regression, while MECOM loss induces tumor growth arrest/stasis." (PMID 33903593, 2021). "The dual PAX‐8 and E‐cadherin IHC confirmed that the loss of E‐cadherin was associated with the surrounding PAX‐8‐positive ccRCC tumour cells." (PMID 33665979, 2021). "The expression of CDH2, MDM2 and TNFSF10 was significantly upregulated in tumor tissue, while expression of PAX8 and FERMT2 was significantly downregulated." (PMID 33850477, 2021). "The findings in the three HCC of our cohort (i.e., two cases with PAX8/PPARγ rearrangements and one wild-type tumour) were quite unexpected." (PMID 32638211, 2021). "Using ChIP-seq across a panel of HGSOC cell lines, we demonstrated that LYPD1 is a PAX8 lineage-driven tumor antigen and tractable cell-surface drug target in HGSOC." (PMID 34290299, 2021). "Herein, we describe the transcriptional regulation of LYPD1 expression by PAX8 in HGSOC tumor cells." (PMID 34290299, 2021). "Pax2 is related to chromosomal translocation in tumor cells and the development of kidney, central nervous system (CNS), and optic nerve, while Pax8 is involved in thyroid, CNS, and kidney cell development." (PMID 34824296, 2021). "Although all RCC tumor cells are positive for PAX8, a marker of renal origin, the distinct immunophenotypic characteristics of CCP RCC include strongly diffuse CK7 and CA-IX expression." (PMID 31851455, 2020). "Remarkably, the FCT tumour positive for PAX8/PPARγ rearrangement also harboured a RET/PTC1 rearrangement." (PMID 32659948, 2020). "Histology confirmed the micropapillary and cribriform growth pattern with intraluminal tumor budding and positivity for PAX8 and WT1." (PMID 32317693, 2020).
tumor (continued). "We identified genes that are both differentially expressed and methylated in the two tumor subtypes, concentrating on PAX8 as a bona fide marker of FI-like HGSOC." (PMID 33121525, 2020). "By contrast, OCMs 46, 66 and the other the HGSOC tumours were PAX8 positive, consistent with a fallopian tube origin." (PMID 32054838, 2020). "Nevertheless, CD99 and PAX8 specificity is limited in ES because its immunoreactivity is commonly observed in many other tumours." (PMID 32675940, 2020). "This indicates a high sensitivity; however, it is known that both CD99 and PAX8 are also expressed in other tumours." (PMID 32675940, 2020). "Of note, TERT mRNA expression levels were not different when considering other genetic alterations present in the tumours, such as BRAF, NRAS mutations and RET/PTC or PAX8/PPARγ rearrangements (Figure A1)." (PMID 32659948, 2020). "Our results demonstrate that PAX8 modulates the interaction of tumor cells with the extracellular matrix (ECM)." (PMID 31832016, 2019). "First, in the sense of tumor biology, we delineate a functional lineage-specific PAX8 regulon in ovarian carcinoma, as exemplified by the PAX8-FGF18 regulatory axis acting autocrinely to facilitate cell migration." (PMID 31050342, 2019). "In the mesothelial lining of the peritoneum covering the abdominal wall, more inflammatory and tumor cells of ovarian origin were detected, as confirmed by a positive PAX-8 staining." (PMID 31619730, 2019). "(B) GSEA plots indicated downregulation of cell cycle or tumor metastasis related gene sets upon PAX8 knockdown in OVTOKO cells." (PMID 31050342, 2019). "While our data strongly argued that PAX8 was a rational target in EOC to inhibit both tumor growth and dissemination, the pharmaceutical development of therapeutic strategies against transcription factors had been extremely challenging." (PMID 31050342, 2019). "A high degree of Pax8 (tumor marker) and pY397 FAK co-localized staining was detected in primary biopsy samples with FAK pY397 exhibiting both cytoplasmic and nuclear localization." (PMID 31478830, 2019). "Immunohistochemically, tumor cells were diffusely positive for PAX8, keratin (AE1/AE3), epithelial membrane antigen (EMA) and CK7." (PMID 31627758, 2019). "Reminiscent of our in vitro findings, tumor development in mice was significantly hampered upon PAX8 knockout compared with the control group, as measured by the bioluminescence imaging." (PMID 31050342, 2019). "Gene set enrichment analysis (GSEA) pinpointed the anticipated suppressed pathways related to cell cycle upon PAX8 knockdown, and of interest, multiple significantly altered signaling modules promoting tumor metastasis." (PMID 31050342, 2019). "To have better insights into the PAX8-ITGB3 regulatory network, we performed a putative gene network analysis involving ITGB3 as a mediator of PAX8 in cell–cell interaction (contact inhibition) and cellular adhesion (tumor growth)." (PMID 31832016, 2019). "(A) IHC staining of paraffin-embedded serial initial tumor biopsy sections (patient 3000276) with H and E, Pax8, pY397 FAK, and Ki67." (PMID 31478830, 2019).
tumor (continued). "In order to confirm that the cell line and tumors were composed of fallopian tube secretory cells derived from the HGSOC mouse model, PAX8 marker staining was performed on the 3666 cell line as well as sectioned tumor from control xenograft #58." (PMID 31134152, 2019). "Analysis of tumor angiogenesis by CD31 immunostaining revealed that PAX8 overexpression led to a significant decline in the CD31-positive MVD." (PMID 30021604, 2018). "Pax8 also promoted tumor cell growth by increasing transcription of the cell cycle regulator E2f1 through direct binding to the E2f1 promoter in a complex with the RB protein." (PMID 30096791, 2018). "In vivo studies further demonstrated that PAX8 overexpression restrained tumor angiogenesis and metastasis in nude mice, which was accompanied by increased expression of miR-612 and decreased expression of FOXM1." (PMID 30021604, 2018). "Knockdown of miR-612 or overexpression of FOXM1 significantly reversed the tumor-suppressive activity of PAX8." (PMID 30021604, 2018). "Cluster analysis and analysis of CK7 and PAX8 expression on cells, isolated from peritoneal fluid, were used for the prediction of primary tumor origin." (PMID 30024911, 2018). "Pax-8 is helpful for determining renal origin, but is also positive in tumours from other sites, such as the thyroid gland and gynaecological tract tumours of Müllerian origin." (PMID 30123932, 2018). "The PAX8-PPARγ translocations are found in 35% of FTC and vascular invasion and tumor proliferation have been linked to these translocations." (PMID 29455653, 2018). "KDM4B was expressed in hypoxic regions of tumor epithelium as determined by pimonidazole and PAX8 staining (respectively)." (PMID 27869162, 2017). "Immunohistochemistry showed the tumour cells to strongly express PAX8, Vimentin, CAM5.2, AMACR and EMA, focal E-cadherin expression with no tumour expression of CD10, RCCAg, CK7, or CD117." (PMID 27005674, 2016). "Despite its ubiquitous expression and role in other tumor types, little is known about what PAX8 regulates in HGSC." (PMID 27129161, 2016). "We compared a published microarray dataset of WT1-mutant and WT1-wild-type tumours to the Nes-Cre Wt1 conditional and Pax8+/CreWt1 conditional datasets." (PMID 26035382, 2015). "The tumor cells were also positive for PAX-8, which is a transcription factor expressed in both normal and neoplastic thyroid, kidney, and female genital tract." (PMID 26351607, 2015). "Equally, the post-MET/early tubulogenesis block found in the Pax8+/CreWt1co kidneys more resembles the epithelial nature of WT1-wild-type tumours." (PMID 26035382, 2015). "Using IHC analysis, PAX8 protein expression was determined in archival NSCLC tumor tissues (n = 254)." (PMID 24628993, 2014). "Seven tumours showed less than a 2-fold increase in the PAX8 expression compared to HEK-293 cells and were typed as PAX8-negative tumours." (PMID 24602166, 2014). "The suppression of PAX8 was associated with a reduction in both cell growth and BCL2, suggesting that a reduction in PAX8 expression would sensitise tumours to cell death." (PMID 24602166, 2014). "All PAX8-positive tumours were verified as positive using another PAX8 antibody raised against a region of the C-terminus, which exhibits a lower homology with PAX5." (PMID 24602166, 2014). "Utilizing early progenitors isolated from NSCLC cell lines and fresh tumor tissues, we observed robust overexpression of PAX8, MET, and RON." (PMID 24628993, 2014). "The tumour-promoting functions of PAX8 include the ability to transform cells and to form tumours in mice, an increased telomerase activity, and the promotion of cell cycle progression." (PMID 24602166, 2014). "All tumours had intense PAX8 immunostaining with the exception of the ALT-positive tumours, of which 4/8 ALT-positive tumours showed faint PAX8 immunostaining." (PMID 24602166, 2014). "A number of studies have found that PAX8 is important for the development of various types of tumor." (PMID 23425942, 2013).